EGFR (epidermal growth factor receptor)
Diseases named in the same sentence as EGFR in open-access papers (continued):
Sharing a sentence is not in itself a finding about the gene and the disease.
lung cancer (continued). "Furthermore, we also evaluated the antiproliferative activity of compound 18 in EGFR mutated lung cancer cell line NCI-H1975." (PMID 29088782, 2017). "Overall, the present study offers a new strategy to increase the initial clinical response rate in EGFR‐mutated lung cancer patients by providing a molecular rationale for using EGFR‐TKI in combination with AKT inhibitor in patients harboring high RHOB tumor levels." (PMID 28003335, 2017). "A sensitive and convenient method for detecting epidermal growth factor receptor (EGFR) T790M mutations from circulating tumor DNA (ctDNA) in advanced non–small cell lung cancer (NSCLC) patients with acquired EGFR‐TKI resistance would be desirable to direct patient sequential treatment strategy." (PMID 28000387, 2017). "The dedifferentiation of cancers from adenocarcinoma to small-cell carcinoma is more commonly observed in EGFR mutated lung cancer and may confer sensitivity to platinum-based therapies." (PMID 28487881, 2017). "By optimizing competitive allele‐specific TaqMan PCR (CAST‐PCR), we assessed the copy number of mutated Kirsten rat sarcoma viral oncogene homolog (KRAS) and epidermal growth factor receptor (EGFR) alleles in the pre/post surgery plasma of 168 lung cancer patients." (PMID 28382702, 2017). "Therefore, it is very helpful to identify the subtype of EGFR mutation in the clinical treatment of lung cancer." (PMID 28336963, 2017). "EGFR TKIs improve outcomes for patients with lung cancer harboring activating EGFR mutations." (PMID 28396848, 2017). "Here we found an inverse correlation between the USP24 level and EGFR mutations in lung cancer clinical samples, suggesting that USP24 might negatively regulate cancer formation." (PMID 27991932, 2017). "In addition, in EGFR mutated lung cancer cells, miR-218 can also negatively regulate pSTAT3 signaling through targeting EGFR." (PMID 28830450, 2017). "Therefore, in contrast to lung cancer, our data with ovarian cancer cells suggested that sialylation was positively associated with EGFR function." (PMID 28423672, 2017). "The determination of the EGFR mutation status is crucial for the personalized treatment in patients with lung cancer and provides a molecular target that may be treated using anti-EGFR drugs." (PMID 28068946, 2017). "Several randomized clinical trials have shown that first‐generation EGFR tyrosine kinase inhibitors (TKIs), including gefitinib and erlotinib, and second‐generation EGFR‐TKIs, including afatinib, achieved a good clinical response in lung cancers harboring activating EGFR mutations." (PMID 28388009, 2017). "Complete and partial response could also be potential surrogate markers for predicting overall survival in lung cancer patients with EGFR mutations." (PMID 28388009, 2017). "Activating mutations in EGFR are well-described predictors of response to erlotinib in lung cancer." (PMID 27853997, 2017). "Also, 1,25(OH)2D inhibits signaling pathways that promote lung cancer including mutations in K-Ras and epidermal growth factor receptor (EGFR), dysregulation of Wnt/β-catenin, which determines metastasis and proliferation." (PMID 29113365, 2017). "If information for a single mutation is needed (i.e., EGFR T790 M for targeted therapy in lung cancer) for treatment choices, direct PCR might be suitable." (PMID 28468669, 2017). "Notably, lung cancers are usually accompanied by the mutation of the epithelial growth factor receptor (EGFR) and its high expression." (PMID 29152147, 2017). "Thus, lung cancer patients with EGFR mutations have superior therapeutic options and outcomes compared with other patients." (PMID 27835914, 2017). "We reported that in afatinib-resistant sublines derived from the lung cancer cell line PC9 that harbors an activating EGFR mutation, the levels of multiple EGFR family proteins are markedly reduced and accompanied by compensatory activation of an FGF2/FGFR1 autocrine signaling pathway." (PMID 29050315, 2017).
lung cancer (continued). "Therefore, we conducted a study to investigate the association of family history of lung cancer with EGFR activating mutation and the prognostic impact in a prospective lung cancer cohort." (PMID 28486527, 2017). "However, using a nationwide database, a large sample size was derived and adequate statistical power was provided to examine the association between statins and mortality in patients with EGFR-TKI lung cancer." (PMID 28158206, 2017). "Our study of lung cancer cells harboring the EGFR T790M mutation showed that all of the tested EGFR-TKIs, except for erlotinib, effectively inhibited the phosphorylation of the EGFR, AKT, and ERK." (PMID 29285266, 2017). "However, a previous study has demonstrated mutation rate of EGFR in lung cancer differs between races." (PMID 29190914, 2017). "EGFR activating mutations are associated with prognosis in patients with lung cancer." (PMID 28486527, 2017). "For example, mutations in EGFR are associated with lung cancer." (PMID 28415609, 2017). "However, further studies with different EGFR-TKIs (e.g. erlotinib or afatinib) and EGFR-TKI sensitive lung cancer cells are still advocated to elucidate further the underlying interaction mechanism of EGFR-TKIs and statins." (PMID 28158206, 2017). "An Italian group recently reported results wherein a cohort of lung cancer cytological specimens where analysed using the IdyllaTM EGFR Mutation assay (Biocartis), which detects 53 different mutations (point mutations, insertions and deletions) using integrated PlexPrime/PlexZyme technology." (PMID 28114309, 2017). "Hyperactivation of EGFR is closely associated with the development and progression of lung cancer." (PMID 27757846, 2017). "EGFR mutation and EGFR-TKI resistance also exist in lung cancer with DS." (PMID 28903458, 2017). "Accordingly, the effect of the BIM deletion among the South American population should also be examined, particularly since the EGFR mutation rate and therefore proportion of EGFR-TKI-responsive lung cancers in South American populations is higher than reported in European studies." (PMID 28467813, 2017). "We obtained similar results for both EGFR-wild type and EGFR-mutated lung cancer patients." (PMID 28978016, 2017). "This review summarizes known mechanisms of TKI resistance, clinical approaches to resistance with a focus on third-generation EGFR TKIs, their preclinical and clinical evidence for use, and future directions to improve the outcomes of patients with EGFR mutation-positive lung cancer." (PMID 28620581, 2017). "This phenomenon might be explained as follows: More male squCA and female adenoCA (WT EGFR) patients were smokers, and smoking-related lung cancers have more genetic mutations, with a higher potential of distant metastasis or local failure." (PMID 27835914, 2017). "Clinicians should consider EGFR mutation and EGFR-TKIs resistance in lung cancer patients with DS." (PMID 28903458, 2017). "For lung cancer patients who has EGFR mutation, an initial treatment with EGFR TKI is preferred." (PMID 28615068, 2017). "The underlying mechanism of how statins enhance the effect of EGFR-TKIs in lung cancer cells and patients remains unclear." (PMID 28158206, 2017). "Consequently, mono‐ or combo‐therapies using the modified drug doses were tolerable, but the effect was insufficient to inhibit lung cancer cells harboring EGFR T790M mutations." (PMID 28388009, 2017). "Additionally, this process is likely involved in EGRF-TKI-based therapy resistance in both EGFR-non mutated (A549) and EGFR-mutated (H1975) lung cancer cells." (PMID 28978016, 2017).
lung cancer (continued). "Our study found that younger smokers had a lower EGFR mutation rate, which may be due to the dilution of the effect of more smoking-related lung cancer." (PMID 29228697, 2017). "EGFR is a major therapeutic target in EGFR mutated lung cancers." (PMID 28198463, 2017). "Lung cancer patients whose tumors express mutated EGFR often benefit from drug exposure." (PMID 29296175, 2017). "A somatic EGFR p.E746_S752delinsA mutation in a mediastinal metastasis from a breast cancer prompted its anatomopathologic reassessment, its definite reclassification as a lung cancer and its treatment with gefitinib (partial response sustained for 15 months)." (PMID 28717660, 2017). "Furthermore, CRP has been noted as a marker of lung cancer risk and interestingly, as a predictor of response to anti-EGFR gefitinib therapy." (PMID 28402963, 2017). "Compared to wild type EGFR, proteins coded for with the gene with the T790M mutation have a 5-fold increased efficacy of kinase activation; this increased activity is responsible for the poor outcome of lung cancer patients." (PMID 27902463, 2017). "High rates of EGFR mutations in Peruvian patients with non–small-cell lung cancer could be a signature of Asian ancestry in the Peruvian population." (PMID 28831453, 2017). "Despite the advancement of EGFR inhibitors in lung cancer therapy, it remains unclear whether EGFR mutation status in familial lung cancers is different from that of sporadic cases." (PMID 27449093, 2016). "Furthermore, hypoxia increases the population of lung cancer stem cell resistant to gefitinib in EGFR mutation-positive NSCLC by activating IGF1R." (PMID 27463019, 2016). "Indeed, by analysis of mutations, ctDNA was identified in only 62% of EGFR-mutated lung cancer patients, as compared to 92% of KRAS-mutated colon-cancer patients." (PMID 28027313, 2016). "In addition, exon 19 deletion mutation of the EGFR gene was associated with increased angiogenic ability in lung cancer cells, which was inhibited by a knockdown of CDH5 siRNA." (PMID 27362942, 2016). "Moreover, the distribution of EGFR mutation subtypes among patients with lung cancer family history was random." (PMID 27449093, 2016). "Although earlier studies did not suggest a significant effect of inherited predisposition on development of lung cancer in twins, they remain important candidates in research into the genetic familial effects on EGFR mutagenesis because of their genetic similarity." (PMID 27449093, 2016). "Ethnical origins and different risk factors for lung cancer might explain the distinct mutation profiles, as in the case of epidermal growth factor receptor (EGFR) and KRAS for Asians, Caucasians and Latins." (PMID 27098372, 2016). "Increased expression CDH5 is observed in lung cancer cells with EGFR mutations." (PMID 27362942, 2016). "Many lung cancer driver gene mutations have been identified, such as EGFR, KRAS, ROS, EML4-ALK." (PMID 27223066, 2016). "Similarly, the resistance to gefitinib is acquired in lung cancer by a mutation of EGFR gene, a target molecule of gefitinib." (PMID 26769852, 2016). "Overexpression of PD-L1 has been implicated as a mechanism of immune-evasion in lung cancer as well as other solid tumors, and has been reported to be associated with the presence of sensitizing EGFR mutations in selected lung cancer cell lines and resected non-small cell lung cancer." (PMID 27467256, 2016). "Epidermal growth factor receptor (EGFR) mutation plays an oncogenic role in lung cancer initiation." (PMID 27786281, 2016). "Gefitinib therapy may be a suitable treatment for brain metastasis in lung cancer with an epidermal growth factor receptor mutation, particularly in elderly patients with a poor performance status." (PMID 26724810, 2016). "However, in most of those studies, the EGFR mutation status was tested using surgically resected PT and LN specimens from operable lung cancer patients." (PMID 27685950, 2016).
lung cancer (continued). "Furthermore, a study indicated that the expression of cytoplasmic YAP1, which is the inactive form, was associated with longer-progression free survival and overall survival in EGFR-TKI-treated lung cancer patients with EGFR mutations." (PMID 26716514, 2016). "Despite the advancement of epidermal growth factor receptor (EGFR) inhibitors in lung cancer therapy, it remains unclear whether EGFR mutation status in familial lung cancers is different from that of sporadic cases." (PMID 27449093, 2016). "The patients included in that study all had operable lung cancers, and the investigators used a TheraScreen EGFR mutation kit (DxS, Manchester, UK) to detect 28 specific mutations; some samples were further analyzed by denaturing high-performance liquid chromatography and sequencing." (PMID 27655296, 2016). "Our study summarized the characteristics of Chinese lung cancer patients with EGFR mutations." (PMID 26739511, 2016). "Thus, personalized therapeutics should be developed to direct the use of these drugs in the treatment of EGFR-mutated lung cancer." (PMID 27456471, 2016). "Physiologic supplementation might be exploited to prevent disease recurrence among vitamin D-deficient individuals diagnosed with early stage EGFR mutant lung cancer who undergo surgical resection with curative intent." (PMID 26654942, 2016). "Notably, H292 lung cancer cells have EGFR amplification while PC-9 lung cancer cells harbor the EGFR exon 19 deletion mutation." (PMID 27705911, 2016). "Further studies are warranted to elucidate the clinical and/or biological significance of acquired PIK3CA mutations, KRAS mutations and uncommon EGFR (other than p.T790M) mutations as well as other co-existing resistance mutations in TKI-resistant lung cancers." (PMID 27304188, 2016). "At this stage, it is unknown how DUOX1 silencing relates to different types of lung cancer or with specific mutations in EGFR, KRAS and so on." (PMID 27694834, 2016). "As a result, increased phosphorylation of EGFR in stable lung cancer cells with exon 19 deletion mutation may be due to distinct conformational changes within the catalytic pocket." (PMID 27362942, 2016). "The retrospective familial lung cancer cohort, including lung cancer patients with at least 2 tumor tissues available within a family, were indicated as “Cohort-2” to evaluate the intra-family distribution of EGFR mutations." (PMID 27449093, 2016). "KRAS and EGFR represent two most commonly mutated oncogenes in lung cancer with distinct biology." (PMID 27485414, 2016). "As stem-like cells have been shown to contribute to radioresistance, combined EGFR/Notch targeting in lung cancer cells bearing activating mutations in EGFR could offer a very powerful approach to reduce the radiation resistant populations." (PMID 26713603, 2016). "Unlike colon carcinoma, where tumors harboring mutant KRAS are known to be resistant to EGFR inhibition, the significance of KRAS mutations upon the benefit of anti-EGFR therapies in patients with lung cancer remains unclear." (PMID 27248176, 2016). "One of these could be the presence of specific driver mutations, such as oncogenic RAS or EGFR signaling, as seen in lung cancer." (PMID 27191495, 2016).
lung cancer (continued). "Given that 67.6% of lung-cancer patients have been diagnosed in advanced stages, chemotherapies including molecular-drug-targeted mutations of epidermal growth factor receptor (EGFR) remain the best and standard strategies for lung cancer treatments after surgery." (PMID 27119499, 2016). "A causal role for 25D3 in controlling growth of EGFR mutant lung cancer remains to be established." (PMID 26654942, 2016). "Thus, we down-regulated SCD1 in an EGFR activation mutation lung cancer cell lines H1650 and investigated the ability of cell proliferation and invasion." (PMID 27223066, 2016). "Due to its ability to reverse poor PS and achieve the total regression of brain metastases, EGFR-TKI therapy may be a suitable treatment for brain metastasis in lung cancer with an EGFR mutation, particularly in elderly patients with poor PS." (PMID 26724810, 2016). "Furthermore, we also showed that common EGFR mutations (exon 19 deletion and exon 21 missense L858R) were associated with increased migration and invasion in the lung cancer cells studied." (PMID 27362942, 2016). "Similarly, gefinib, an approved treatment for non-small cell lung cancer target EGFR which is mutated and the cause for aberrant signaling in a set of lung cancer patients." (PMID 27863392, 2016). "Another reason for it may be that Chinese patients were more likely than the other Asian patients to be diagnosed with adenocarcinoma or BAC, which are associated with more EGFR mutations than are the other histologic subtypes of lung cancer we studied." (PMID 27244238, 2016). "Since EGFR TKIs are mainly used to treat lung cancer patients with metastatic diseases, differences in EGFR and K-ras mutations between the primary and metastatic sites may influence the outcome of such a therapy." (PMID 27070580, 2016). "Our previous study has also indicated that the HPV16/18 E6 oncoprotein may contribute to EGFR mutations through inhibited hMLH1 and hMSH2 gene expression in Taiwanese lung cancer patients." (PMID 26918347, 2016). "We have further described that WSE related lung cancer is associated with an older age at diagnosis, adenocarcinoma histology, pleural effusion, high prevalence of EGFR mutations (55.4 %) and a low prevalence of KRAS mutation (6 %), compared to patients with smoking history." (PMID 27098372, 2016). "We investigated whether a cyclin D kinase 4/6 (CDK4/6) inhibitor, PD 0332991, could reverse EGFR-TKI resistance in human lung cancer cells and explored the underlying mechanisms." (PMID 27825114, 2016). "Therefore, effective alternatives are desperately needed in the clinic for treating EGFR mutation-positive lung cancer patients." (PMID 26654941, 2016). "Moreover, size-selecting for shorter cell-free DNA fragment lengths substantially increased the EGFR T790M mutant allele frequency in human lung cancer." (PMID 27428049, 2016). "PD-L1high lung cancer cell lines were associated with a higher expression of EGFR compared to PD-L1low lung cancer cell lines, suggesting that not only sensitive EGFR mutation but also overexpression of EGFR is associated with a higher baseline expression of PD-L1." (PMID 27467256, 2016). "A systematic review of pharmacological interventions performed on GEMMs of lung cancer suggest that with respect to the most clinically relevant mutations, such as those in EGFR and ALK, GEMMs well recapitulated the features of human tumours in terms of response and resistance mechanisms." (PMID 27350784, 2016). "Furthermore, smoking status and EGFR mutation were important factors in the current lung cancer study." (PMID 27191886, 2016). "The most recurrent genetic alterations in non-small cell lung cancer (NSCLC, 85% of lung cancers) consist of mutations in the epidermal growth factor receptor (EGFR) gene, leading to uncontrolled cellular proliferation, inhibition of apoptosis and thus, tissue growth and cancer." (PMID 27416070, 2016).